CASC11 (cancer susceptibility 11)
Diseases named in the same sentence as CASC11 in open-access papers (continued):
Sharing a sentence is not in itself a finding about the gene and the disease.
prostate tumor (1 paper, 2020). "When we incorporated RNA expression data in prostate tumor tissue, we observed significant inverse associations between tumor MYC DNA methylation and expression of the lncRNAs PRNCR1 and CASC11, and a significant positive association with miR-1206 expression." (PMID 33374332, 2020).
cancer (23 papers, 2017 to 2025). A tumor composed of atypical neoplastic, often pleomorphic cells that invade other tissues. "We have found a correlation between cancer susceptibility candidate 11 (CASC11) experssion and tumorigenesis development prognosis in a number of studies on tumors." (PMID 39686470, 2024). "The results revealed that the overexpression of CASC11 was significantly associated with poor OS (hazard ratios = 2.07, 95%CI = 1.64–2.60) in cancer." (PMID 39686470, 2024). "Further subgroup analysis demonstrated that the overexpression of CASC11 was consistently linked to poorer OS in diverse types of cancer, including digestive system neoplasm, respiratory neoplasms, and gynecologic tumor." (PMID 39686470, 2024). "The long non-coding RNA (lncRNA) cancer susceptibility 11 (CASC11) is a newly identified lncRNA located on chromosome 8q24.21." (PMID 37427385, 2023). "We further evaluated the expression levels of c-Myc and cancer susceptibility candidate 11 (CASC11) located in the chromosome 8q24 gene desert (2.1 kb upstream of c-Myc)." (PMID 36728436, 2023). "Cancer susceptibility candidate 11 (CASC11) has been shown to play an important role in a variety of cancers, including HCC." (PMID 36901717, 2023). "Up-regulation of CASC11 has been associated with higher pathological stage and lower overall survival rate in this cancer (Chen SG." (PMID 37427385, 2023). "The long non-coding RNA, cancer susceptibility candidate 11 (CASC11), is a recently discovered molecule that has been shown to be upregulated in multiple human cancers." (PMID 37552314, 2023). "Taken together, CASC11 is an oncogenic lncRNA with possible application as diagnostic and prognostic marker in cancer." (PMID 37427385, 2023). "Here, it should be noted that LncRNA cancer susceptibility candidate 11 (CASC11) is a novel lncRNA and has been revealed to be upregulated in several human cancers, including colorectal cancer (CRC), gastric cancer, bladder cancer, and ovarian cancer." (PMID 34900723, 2021). "Yet, three are several unsolved questions about the underlying mechanism of CASC11 up-regulation in cancers, possible impact of genetic polymorphisms on its function and activity, the role of epigenetic factors in its regulation and the interactions between CASC11 and other regulatory biomolecules." (PMID 37427385, 2023). "Besides, it has been revealed that long non-coding RNA (LncRNA) cancer susceptibility candidate 11 (CASC11) is involved in cancer progression." (PMID 34900723, 2021). "The cancer susceptibility candidate 11 (CASC11) lncRNA is among them." (PMID 31379917, 2019). "First, all the patients included in the study were Chinese, so the predictive value of CASC11 for malignant tumor patients in other countries and regions requires further investigation." (PMID 39686470, 2024). "This meta-analysis was performed to analyze the potential relationship between CASC11 expression level and prognosis of cancer patients by including relevant articles." (PMID 39686470, 2024). "Further subgroup analysis was performed to assess various factors such as cancer type, method used to obtain hazard ratio, sample size, and the cutoff value for CASC11 expression." (PMID 39686470, 2024). "Overall, this analysis established a strong correlation between CASC11 expression and tumor prognosis, suggesting its potential as a predictive marker for tumor progression in diverse cancer types." (PMID 39686470, 2024). "It has been suggested that the high expression of CASC11 is a key factor in the poor prognosis of cancer patients." (PMID 39686470, 2024). "The expression of lncRNA CASC11 has been found to be elevated in different cancer types and the prognosis of the tumor is inversely correlated with the high CASC11 expression." (PMID 37427385, 2023). "Over-expression of CASC11 promotes, while miR‐150 overexpression inhibits cancer cell proliferation." (PMID 37427385, 2023).
cancer (continued). "Cell line assays to determine function of CASC11 in various cancer types (TCLs: tumor cell lines, NCL: normal cell line, ∆: knockdown or deletion, EMT: epithelial-mesenchymal transition)." (PMID 37427385, 2023). "The data summarized in this manuscript highlights the importance of CASC11 in the carcinogenesis and suggests this lncRNA as a putative target for anti-cancer therapies." (PMID 37427385, 2023). "Given the versatile mechanisms of action of CASC11 in a variety of cancer types, we decided to explore the mechanisms of CASC11 as a ceRNA in CRC progression." (PMID 33937069, 2021). "Several past studies have reported that, as an oncogene, CASC11 participates in various biological processes of malignant tumours." (PMID 33937069, 2021). "Conversely, overexpression of CASC11 facilitated the cancer cell’s proliferation, migration and invasion ability and suppressed the apoptosis." (PMID 31255182, 2019). "Comparing with adjacent non-cancer tissues, CASC11 was significantly up-regulated, while miR-188-5p was significantly down-regulated in HCC tissues (P<0.05)." (PMID 30910841, 2019). "Conversely, overexpression of CASC11 facilitated the cancer cell growth and suppressed the apoptosis." (PMID 31255182, 2019). "Recently, a large number of studies have demonstrated that CASC11 plays a crucial role in multiple signal transduction pathways, leading to a deeper understanding of its involvement in the occurrence and development of malignant tumors." (PMID 39686470, 2024). "However, no previous studies have investigated the relationship between CASC11 and prognosis in cancer patients." (PMID 39686470, 2024). "Upregulation of CASC11 could facilitate cancer cell proliferation, migration and invasive abilities and suppress their apoptosis." (PMID 37427385, 2023). "As a result, lncRNA CASC11 has an oncogenic function in cancers." (PMID 37427385, 2023). "Therefore, a complex network exists between cancer-related transcription factors, CASC11 and miRNAs." (PMID 37427385, 2023). "Animal models of cancer showing impact of CASC11 (∆: knockdown or deletion)." (PMID 37427385, 2023). "The role of CASC11 in the carcinogenesis has been evaluated in several cancer cell lines." (PMID 37427385, 2023). "Functionally, CASC11 enhances proliferation and metastasis in cancer cells." (PMID 34900723, 2021). "Recently, the molecular mechanism of CASC11 has been well elucidated in some cancers." (PMID 34900723, 2021). "CASC11 acts as an oncogene in several kinds of human cancers." (PMID 34900723, 2021). "In addition, miR-188-5p overexpression attenuated the enhancing effects of CASC11 overexpression on cancer cell proliferation." (PMID 30910841, 2019). "Therefore, LncRNA CASC11 promoted cancer cell proliferation in HCC possibly by inhibiting miR-188-5p." (PMID 30910841, 2019). "In addition, miR-188-5p overexpression attenuated the enhancing effects of CASC11 overexpression on cancer cell proliferation (P<0.05)." (PMID 30910841, 2019). "Furthermore, CASC11 can act both as a therapeutic target and a cancer biomarker." (PMID 39686470, 2024). "Interestingly, it was noted that cancer patients with high CASC11 expression had worse DFS." (PMID 39686470, 2024). "Thus, CASC11 is a putative prognostic marker for diverse cancers." (PMID 37427385, 2023). "Moreover, lncRNA CASC11 has an oncogenic function in cancers." (PMID 37427385, 2023). "In addition, miR‐150 could attenuate the increasing effect of CASC11 upregulation on proliferation of cancer cells." (PMID 37427385, 2023). "Therefore, CASC11 could potentially serve as a biomarker and therapeutic target for cancer." (PMID 39686470, 2024). "Expression of CASC11 and miR-188-5p in HCC and adjacent non-cancer tissues was analyzed by performing RT-qPCR experiments." (PMID 30910841, 2019). "In contrast, the correlation between CASC11 and miR-188-5p was not significant in non-cancer tissues." (PMID 30910841, 2019).
cancer (continued). "In conclusion, the findings of this meta-analysis revealed that the elevated expression of lncRNA CASC11 could serve as a negative factor when assessing the clinical outcome of cancer patients." (PMID 39686470, 2024).
tumor (19 papers, 2017 to 2025). "On chromosome 8q24, there is a gene known as CASC11 whose expression in CRC patients was discovered to be linked with tumor growth, and it is elevated in CRC cells and tissues." (PMID 38294554, 2024). "CASC11 expression was significantly associated with the tumor grade and metastasis, while Kaplan-Meier method and the log-rank test demonstrated that high CASC11 expression was correlated with the poor overall survival rate of HCC patients to some extent." (PMID 34900723, 2021). "Furthermore, the study revealed a positive association between high levels of CASC11 expression and key indicators of tumor development, such as the tumor size, serous infiltration, lymph node metastasis, and TNM stage." (PMID 39686470, 2024). "The relationship between the expression level of CASC11 and clinicopathologic features in neoplasms." (PMID 39686470, 2024). "Our data demonstrated that PVT1 circular RNA (CircPVT1), MYC, and CASC11 are significantly (p < 0.05) overexpressed in CRC tumor samples compared to normal margin tissues." (PMID 36052265, 2022). "In terms of ubiquitin-conjugating enzyme E2T (UBE2T), it was the most enriched transcript pulled down by CASC11, and has been reported to contribute to tumor growth and metastasis." (PMID 34900723, 2021). "In this context, here, it was found that CASC11 was upregulated in HCC tissues and associated with tumor grades, metastasis, and prognosis of HCC patients." (PMID 34900723, 2021). "The patients were divided into two groups by medium cutoff of CASC11 expression level in tumor tissues." (PMID 33252856, 2020). "In this research, the data showed that CASC11 was upregulated in HCC tissues and cells lines, and its high expression was associated with more advanced tumor progression and poorer prognosis." (PMID 33252856, 2020). "Further, the patients were divided into two groups by medium cutoff of CASC11 expression in tumor tissues." (PMID 33252856, 2020). "In the present study, we found that CASC11 was up-regulated, while miR-188-5p was down-regulated in tumor tissues of HCC patients." (PMID 30910841, 2019). "The relative expression of CASC11 detected by RT-qPCR was much higher in the tumor samples than that in the adjacent normal tissues (n = 50 tumor; n = 50 adjacent normal)." (PMID 31255182, 2019). "Tumor formation in nude mice showed that inhibition of CASC11 expression decreased the tumor volumes and weight by reducing the expression of β-catenin." (PMID 31255182, 2019). "Si-CASC11-transfected HeLa cells were subcutaneously inoculated into male athymic (nude) mice to investigate the effect of CASC11 on the tumor formation." (PMID 31255182, 2019). "Cancer susceptibility candidate 11 (CASC11) is overexpressed in CRC tissues and is positively associated with tumor size, serosal invasion, lymph metastasis, and tumor-node-metastasis (TNM) stage." (PMID 27888635, 2017). "Moreover, miR-646 and miR-381-3p inhibitors have been shown to reverse the inhibitory effects of CASC11 silencing on tumor growth and metastasis." (PMID 37427385, 2023). "Moreover, up-regulation of CASC11 in tumor tissues has been related with poor prognosis and adverse clinicopathological characteristics such as metastasis, lymph node involvement, higher grades and advanced stages." (PMID 37427385, 2023). "In addition, other reports have demonstrated that CASC11 overexpression is associated with tumor-node-metastasis (TNM) and tumor size in CRC." (PMID 36052265, 2022). "In summary, in CRC, the lncRNA CASC11 acts not only as a tumour promoter that binds to related proteins and activates the Wnt/β-catenin pathway but also as a sponge of miR-646 and miR-381-3p to upregulate RAB11FIP2 and regulate the PI3K/AKT pathway, thus promoting CRC progression." (PMID 33937069, 2021).
tumor (continued). "Furthermore, to confirm the promotion of CASC11 in HCC proliferation in vivo, the control and CASC11-overexpressed Huh7 cells were subcutaneously injected into nude mice, and then the tumor growth was examined." (PMID 34900723, 2021). "Expression levels of CASC11 and miR-188-5p were inversely correlated in tumor tissues." (PMID 30910841, 2019). "This suggests that CASC11 may have a role in promoting tumor formation." (PMID 39686470, 2024). "Furthermore, the tumor size correlates with the expression level of CASC11." (PMID 36699052, 2022). "Moreover, CASC11 overexpression facilitated xenograft tumor growth and metastasis in vivo." (PMID 34900723, 2021). "When CASC11 is inhibited in CRC, proliferation and metastasis are suppressed in tumor cells by interacting with heterogeneous ribonucleoprotein." (PMID 36699052, 2022). "Here, our report demonstrated that CASC11 was upregulated in HCC tissues and correlated with the tumor grade and metastasis." (PMID 34900723, 2021). "Functionally, CASC11 facilitated HCC cell proliferation, migration, and invasion in vitro, and enhanced tumor growth and metastasis in vivo." (PMID 34900723, 2021). "Additionally, the suppression of CASC11 in CRC inhibits the spread and proliferation of tumor cells." (PMID 38294554, 2024). "Indeed, different studies identify the lncRNAs CASC11, CCAT1 and RMRP as BC tumor promoters acting as ceRNA." (PMID 37238229, 2023). "In conclusion, CASC11 was overexpressed in HCC and may down-regulate tumor suppressive miR-188-5p to promote disease development." (PMID 30910841, 2019). "The present study showed that high expression level of CASC11 was closely correlated with the poor survival of HCC patients, and overexpression of CASC11 may inhibit HCC by reducing the proliferation of HCC cells through the down-regulation of miR-188-5p, which is a tumor suppressor in HCC." (PMID 30910841, 2019).
digestive system neoplasm (1 paper, 2024). A neoplasm (disease) that involves the digestive system. "Since there was no heterogeneity among the subgroups, a fixed model was used for analysis, our data suggested that increased CASC11 expression in gastrointestinal tumor, respiratory neoplasms, and gynecologic tumor was statistically associated with shorter OS." (PMID 39686470, 2024).
CASC11 also shares sentences with these, for which no sentence is quoted: coronary artery disease (2 papers); artery disease (1); chronic heart failure (1); diabetic nephropathy (1); gynecologic tumor (1); osteosarcoma (1); ovarian carcinoma (1); ovarian squamous cell carcinoma (1); small cell lung carcinoma (1).